FGF2 (fibroblast growth factor 2)
Diseases named in the same sentence as FGF2 in open-access papers (continued):
Sharing a sentence is not in itself a finding about the gene and the disease.
tumor (continued). "We used a series of inhibitors to reverse the FGF2 effect on tumor growth, which elucidated paradoxical growth of cancer cells following FGFR1 inhibition in cells with FGFR1 amplification." (PMID 38553760, 2024). "The synthesis of inflammatory cytokines is seen to be inhibited by the MALAT-1-mediated release of FGF2 from TAMs, but tumor cell growth, migration, invasion, and the development of angiogenesis are promoted." (PMID 38511067, 2024). "Alternatively, FGF2 expression was associated with better prognosis in terms of reduced NPI, lower tumor grade, and HER2-negative status." (PMID 39302921, 2024). "SDC1 exhibited a greater tumor mutational burden (TMB) score, while ERBB2, KDR, FGF2, KIT, FGFR1, and FGF1 showed lower TMB scores." (PMID 38189813, 2024). "This hypoxic microenvironment triggers alternative pro-angiogenesis molecular pathways in tumor or stromal cells within the tumor microenvironment, including FGF-2, HGF, DLL4/Notch, CCL28, and others." (PMID 39075504, 2024). "Compared with the other angiogenic factors, strong positive staining of FGF2 was detected in vascular endothelial cells especially in larger sized tumor vessels (≥ 15 μm)." (PMID 38619734, 2024). "Studies suggest that FB can secrete various factors, including VEGFA, PDGFC, FGF2, and osteopontin, which are known to stimulate angiogenesis in tumor tissues." (PMID 39759522, 2024). "Mice deficient in FGF2LMW experience significant inhibition of tumor metastasis and an increase in the iNOS+/CD206+ ratio (also known as M1/M2 ratio) in TAM, highlighting that the deletion of FGF2 promotes M1 polarization of macrophages." (PMID 38962005, 2024). "Tumor-associated neutrophils secrete a plethora of pro-angiogenic molecules including VEGF, FGF-2, Bv8, IL-17, and MMP-9." (PMID 38580870, 2024). "In summary, our findings unveil a signaling network involving METTL3/FGF2/PI3K/AKT/mTOR in LUAD and shed light on the molecular mechanism underlying tumor malignant progression while holding great significance for targeted therapy in research on LUAD." (PMID 39497721, 2024). "We also observed that LCM generated from either tumor-naïve mice (tnLCM) or from mice bearing TN primary tumors (tbLCM) had a significantly increased concentration of FGF2 compared to control media (p ≤ 0.05)." (PMID 38581619, 2024). "In therapy‐induced tumour senescence, there is an enhanced expression of pro‐angiogenic factors (FGF2, VEGF and PDGFA/B) and MMPs (MMP2/3/7/9/10)." (PMID 39270064, 2024). "For instance, PDGF receptor signaling in CAFs can induce the expression of FGF7 and FGF2, directly contributing to tumor angiogenesis, as evidenced by the impairment of angiogenic phenotypes when FGF ligand traps were used." (PMID 38453816, 2024). "H2O2 plays a suppressive role in the tumor microenvironment by enhancing the stimulation of the Fibroblast-FGF2 system." (PMID 37469162, 2024). "Several experiments have confirmed that high expression of FGF2 promotes tumor growth, tumor metastasis, and infiltration of M2-type macrophages in a tumor-bearing mouse model and in vivo tests." (PMID 38962005, 2024). "The expression of FGF1 and FGF2 correlated inversely with tumor size and the Nottingham Prognostic Index (p = 0.03 and p = 0.002, respectively)." (PMID 39302921, 2024). "Bevacizumab-resistant tumor cell-derived FGFBP1 induced fibroblast activation protein α expression by enhancing the paracrine FGF2/FGFR1/ERK1/-2/EGR1 signaling pathway in hepatic stellate cells." (PMID 39668826, 2024). "Plasma fibrinogen promotes tumor cell growth and angiogenesis by interacting with fibroblast growth factor-2 and vascular endothelial growth factor." (PMID 38511137, 2024).
tumor (continued). "In vivo, 99mTc-FGF-2 showed high initial accumulation in the liver, spleen and lungs, followed by tumor localization with high Tumor/Muscle and Tumor/Blood ratios, particularly at 24 h post-injection." (PMID 38672507, 2024). "bFGF/FGF-2 and MMPs also contribute to angiogenesis and tumour progression by modulating extracellular matrix remodelling and destabilizing existing blood vessel walls." (PMID 38794316, 2024). "Elevated expression of FGF2 characterises numerous human tumours, emphasising its crucial contribution in the proliferation and invasion of cancer cells." (PMID 39091947, 2024). "A recent study revealed that targeting DNA methyltransferase 1 (DNMT1) programs immunologically anergic tumor vasculature, and its phosphorylation is promoted by FGF2." (PMID 37864726, 2024). "Hypoxic TAMs promote tumor growth by enhancing the expression of growth factors, such as VEGF, PDGF, and fibroblast growth factor-2 (FGF-2) supporting development of neovasculature within hypoxic areas of the tumor." (PMID 39361163, 2024). "Analysis of the TCGA database in TNBC samples revealed a correlation between the mRNA expression of FGFR1, FGFR2, and FGF2 and the hypomethylation status of tumour cells." (PMID 40135140, 2024). "All the members, notably FGF2, play a pivotal role in tumor angiogenesis by upregulating the proliferation and migration of ECs." (PMID 38672182, 2024). "FGF-2 levels are further augmented in OSCCs, where the cytokine is synthesized by the tumor cells and, possibly, by T cells, monocytes, macrophages, and/or inflamed keratinocytes." (PMID 39120324, 2024). "The results showed that the expression of HNRNPF and FGF2 was elevated in the majority of tumor tissues (T) compared with the matched adjacent non-tumor tissues (N)." (PMID 37968457, 2023). "Neutrophils are also responsible for releasing the factors of tumor-related angiogenesis, including vascular endothelial growth factor, fibroblast growth factor-2, and angiopoietin-1." (PMID 37444448, 2023). "These ADSCs then initiate signaling to drive tumor cell proliferation by secreting FGF2 and activating ERK70." (PMID 36880535, 2023). "FGF2 is involved in a variety of biological processes, including cell growth, morphogenesis, tissue repair, tumor growth and invasion." (PMID 36911388, 2023). "The increased level of FGF2 in tumor microenvironment promotes TAM polarization and infiltration through FGFR1/PI3K/AKT axis, thereby resulting in poor prognosis of GC patients." (PMID 36681667, 2023). "CAFs also express vascular endothelial growth factor (VEGF), platelet-derived growth factor (PDGF), interleukin (IL)-8, epidermal growth factor (EGF), and fibroblast growth factor 2 (FGF-2), ultimately forming a tumour growth supporting microenvironment." (PMID 38041196, 2023). "Despite the fact that hypoxia does not affect the proportion of different macrophage subsets, it does cause the M2-like macrophage subset to activate the transcription of pro-tumor genes, including growth factors like FGF2, PDGF, and VEGF." (PMID 37056346, 2023). "Substances can regulate angiogenesis, tumor proliferation, and metastasis in the extracellular environment via modulating the interactions between FGF-2 and its receptor." (PMID 36765409, 2023). "FGF-2 has been shown to promote tumor progression by increasing the expression of proteolytic enzymes and by paracrine-inducing the growth of vascular endothelial cells." (PMID 37445908, 2023). "FOS, SERPINE1, AKR1C3, and FGF2 are the genes that potentially play important roles in HCC and are associated with tumor growth." (PMID 37057280, 2023). "Our next step was to verify the presence of VEGF-A and FGF2 in the OS tumor before targeting these growth factors pharmacologically and genetically." (PMID 36980704, 2023). "MMP-9 can break down ECM, releasing a variety of angiogenic factors, including VEGF and fibroblast growth factor 2 (FGF2), that act upon nearby endothelial cells to promote tumor angiogenesis." (PMID 37158964, 2023).
tumor (continued). "In liver metastases, neutrophils express FGF2, which can play a role in angiogenesis and tumor progression." (PMID 37371127, 2023). "Typically, E-cadherin protein-expressed recombinant OVs can attenuate antiviral immunity, and fibroblast growth factor 2 (FGF2)-expressed OVs was validated to potentiate the sensitivity of tumor cells toward OVs and promote oncolysis effect." (PMID 37040283, 2023). "Statistical parameters regarding tumor invasion, FGF2 expression pattern and levels, patient demographic characteristics, and disease recurrence were analyzed for significance." (PMID 36843751, 2023). "It has also been reported that FGF2 can shift macrophages towards an M2-like phenotype and alter tumor immunity, which can therefore be a therapeutic target in cancer treatment." (PMID 37090726, 2023). "The additional observation of an increased expression of FGF2 in the dermal portion of some AK lesions also suggested the establishment of aberrant tumor/stromal loops based on the FGF2/FGFR2c axis." (PMID 36979155, 2023). "We have shown that the FGF-2/FGF-21 MN patch has good therapeutic effects in alleviating UVB-induced skin photoaging by reducing inflammation and promoting collagen synthesis both in vitro and in vivo." (PMID 37426882, 2023). "Hypoxic TAMs promote tumor progression and growth of cancer cells via upregulation of grow factors, such as FGF2, PDGF, and VEGF." (PMID 36260158, 2023). "Mechanistically, we unveil that VEGF-B binds to FGFR1, induces FGFR1/VEGFR1 complex formation, and suppresses FGF2-induced Erk activation, and inhibits FGF2-driven angiogenesis and tumor growth." (PMID 37591843, 2023). "MMP-9 activates VEGF and fibroblast growth factor-2 (FGF-2), which promotes vascular endothelial cell proliferation, pro-angiogenesis and signaling, providing nutrition to tumors and promoting tumor metastasis." (PMID 36855112, 2023). "Our study demonstrated that the sEV–vWF/FGF2/FGFR4 cascade mediates tumor–endothelial cellular communication in HCC." (PMID 37387563, 2023). "Mechanistically, we discovered that VEGF-B binds to FGFR1, induces FGFR1/VEGFR1 complex formation, inhibits FGF2-induced Erk activation, and thereby suppresses FGF2-driven angiogenesis and tumor growth." (PMID 37591843, 2023). "CAFs can be formed by attracting fibroblasts of adjacent tissues through transforming growth factor-β (TGF-β), platelet-derived growth factor (PDGF), Fibroblast Growth Factor-2 (FGF-2), and exosomes secreted by tumor cells." (PMID 37666813, 2023). "As seen in other conditions, FGF2 promotes a high mitogenic potential and is involved in many biological processes, including tumor growth and invasion." (PMID 36843751, 2023). "The cytoplasmic expression of FGF2 was evaluated in the tumor stroma and gave a positive reaction in peri- and intratumoral fibroblasts of the stroma and blood vessel endothelial cells." (PMID 36843751, 2023). "sEV–vWF‐activated endothelial FGF2 promotes tumor aggressiveness via positive feedback signaling toward HCC cells through an activated FGFR4‐ERK signaling axis." (PMID 37387563, 2023). "On the other hand, ENPP2 was 2.3-fold up-regulated within tumour-adjacent tissue, and FGF2 was 2.4-fold up-regulated in postmenopausal women compared to premenopausal women." (PMID 37509322, 2023). "In HNSCC, perlecan promotes tumor cell growth, chemoresistance, migration, and invasion, mainly by regulating heparin-binding growth factors such as FGF-2, VEGF-A, and Hedgehog (Hh)." (PMID 38003931, 2023). "FGF2 not only recruits various host cells to the tumor microenvironment (TME) but also enhances VEGFA-dependent neovascularization during tumor progression—a process essential for subsequent tumor growth and metastasis." (PMID 36647777, 2023). "In agreement, transcriptional analyses demonstrated tumour areas were enriched for transcripts encoding numerous growth factors including several fundamental to SSC self-renewal (Gdnf and Fgf2)." (PMID 37564373, 2023).
tumor (continued). "In our study, positive expression of FGF2 was detected by means of IHC in the cytoplasm of fibroblasts in the tumor stroma and around the tumor, as well as in the cytoplasm of endothelial cells from blood vessels." (PMID 36843751, 2023). "The down-regulation of ARID1A, which is a tumor suppressor gene, induces expression of angiogenesis-related genes (particularly VEGF and FGF2) and stimulates angiogenesis independently of ACTB encoding β-actin." (PMID 38017409, 2023). "According to studies: VEGF, IL-8, bFGF/FGF-2, and Matrix metalloproteinases (MMPs), enhance the formation and metastasis of tumor." (PMID 36765409, 2023). "We then analyzed the trend of cancer-promoting factors involved in tumor/stroma crosstalk, such as FGF2, and IL-6, this last systemically elevated in HNSCC patients, linked to resistance to therapy and secreted from stromal fibroblasts in several cancer types." (PMID 36979155, 2023). "FGF2 is a potent EC mitogen, and there are established links between cell cycle inhibition and augmentation of anti-tumor immunity." (PMID 37055433, 2023). "In this initial stage, type I collagen would act by impairing the function of myoepithelial cells as tumor suppressors, by inducing the increase of fibroblast growth factor 2 (FGF-2)." (PMID 37138857, 2023). "Tumor tissue sections used for the initial diagnosis were stained by immunohistochemical means with an anti-FGF2 antibody and the expression within the extracellular matrix was evaluated using a histo-score (h-score)." (PMID 36843751, 2023). "In vivo and in vitro studies showed that antibodies directed against FGF2 and FGF8b have anti-tumor and anti-angiogenic effects." (PMID 35626056, 2022). "Further, FGF-2 has been shown to alter macrophage programming and is a critical regulator of immunity in the tumor microenvironment." (PMID 35725493, 2022). "The action of heparan sulfate-degrading enzymes activates FGF-2 and mediates the process of angiogenesis during both wound healing of normal tissues and tumor development." (PMID 36359244, 2022). "The conditioned medium of NPC tumor cells increased EC proliferation, while knockdown of FGF2 reduced this effect." (PMID 35985991, 2022). "GAL-F2 is a monoclonal antibody targeting FGF2 and was shown to reduce tumor growth in different xenograft mice models of human HCC cell lines: SMMC-7721, HEP-G2, and SK-HEP-1." (PMID 35626056, 2022). "In this study, we investigated the intrinsic AAD resistance mechanisms in NPC and found that NPC is an FGF-2 highly expressing tumor type." (PMID 35985991, 2022). "Another work showed that LMP-1 promotes the expression of fibroblast growth factor 2 (FGF-2), as a potent angiogenic factor involved in tumor invasion, in exosomes derived from cells co-transfected with FGF-2 and LMP-1." (PMID 36437456, 2022). "Our results showed that the combination of bevacizumab with either the FGF2-neutralizing antibody or PD-166866 significantly inhibited tumor growth and reduced the MVD in the bevacizumab-resistant HCT116 and HT-29 CRCLM xenografts." (PMID 35951441, 2022). "Primary human T-ALL cells with HS-5 were injected subcutaneously and BGJ398 or PBS was intraperitoneal injected every 2 days for a total of seven times, the growth of tumours in mice with FGF2 and FGFR2 blockade was slower than control mice (p < 0.05)." (PMID 36333298, 2022). "In response, tumor cells interact with the TME by secreting growth factors (such as FGF-2 and PDGF) and chemokines (such as CXCL12) and induce mechanical stress that ultimately leads to cancer progression." (PMID 35571530, 2022). "In isolated CD31+ ECs from control and shFGF2 NPC tumor tissues, knockdown FGF2 in NPC tumor cells significantly reduced MYC expression in tumor-associated ECs." (PMID 35985991, 2022). "Using gain- and loss-of-function models, we provide compelling evidence that FGF-2 contributes to promoting angiogenesis, TAMs infiltration, and tumor metastasis." (PMID 35439170, 2022).
tumor (continued). "They modulate the TNF-α signaling via direct and indirect effects on the tumor microenvironment, and they reduce the secretion of FGF-2, VEGF and IL-6 by both MM cells and BMSCs." (PMID 36362718, 2022). "FGF2 is correlated with multiple biological processes including tumor growth, apoptosis, and angiogenesis." (PMID 34983591, 2022). "Given the correlation between FGF-2 levels and angiogenesis in NPC tumor tissues, we investigated the functional consequence of FGF-2 on EC cells." (PMID 35985991, 2022). "For almost all patients, IL-16 was detected at higher quantities in the tumor supernatant compared to the juxta-tumor, while the tumor-specific high FGF-2 levels were highly patient-dependent." (PMID 36539890, 2022). "Fibroblast growth factor 2 (FGF2) is a tumor cell survival factor that is transported into the extracellular space by an unconventional secretory mechanism." (PMID 35348113, 2022). "Gain- or loss-of-function experiments revealed that the bevacizumab-resistant tumor cell–derived FGFBP1 induced FAPα expression by enhancing the paracrine FGF2/FGFR1/ERK1/-2/EGR1 signaling pathway in HSCs." (PMID 35951441, 2022). "Activating caspase-1 can either lead to cell death or tumor growth by upregulating the secretion of pro-inflammatory molecules such as IL-1β, IL-18, and FGF2." (PMID 35883451, 2022). "The direct FGF-2 expression of tumor-infiltrating neutrophils was demonstrated in the mouse model of hepatic metastases from gastrointestinal tumors." (PMID 35158807, 2022). "Mechanistically, tumor cell–derived FGF-2 strongly promoted pericyte proliferation and pericyte-specific expression of an orphan chemokine (C-X-C motif) ligand 14 (CXCL14) via FGFR1/AHR signaling." (PMID 35439170, 2022). "FGF2 is the first proangiogenic factors identified in tumors, showing the direct effect on tumor angiogenesis." (PMID 34738872, 2022). "PERK-mediated upregulation of vascular endothelial growth factor (VEGF), fibroblast growth factor-2 (FGF2), and interleukin-6 (IL-6) and downregulation of anti-angiogenic cytokines significantly promoted tumor growth." (PMID 35269473, 2022). "In turn, CAFs produce FGF2 that induces RIG-1 expression in tumor cells, impairing innate immune responses in the tumor cells and promoting OV infection." (PMID 35640930, 2022). "To extend these findings, we treated ESCC tumor-bearing mice (induced by either KYSE30 or EC9706 cells) with FGF2 neutralizing antibody for 20 days and analyzed the effects on tumorigenesis and infiltrated FGFR2+ CAFs." (PMID 35941662, 2022). "When exposed in vitro to VEGF and FGF-2, tumor macrophages differentiated into cells like MM endothelial cells, able to generate in vitro capillary-like networks." (PMID 35158878, 2022). "FGF2 is produced by tumor cells and surrounding stromal cells, and promotes angiogenesis, migration, proliferation, and invasion of tumor cells." (PMID 36118276, 2022). "After subcutaneous injection of primary human T-ALL cells with MSCs, tumour growth was suppressed when FGF2/FGFR2 was interrupted." (PMID 36333298, 2022). "For example, in head and neck and lung cancers, elevated FGF2 levels in tumor or serum have been correlated with an aggressive phenotype and unfavorable prognosis." (PMID 35406617, 2022). "Further evaluation targeting FGF2 pathway on tumor development and tumor microenvironment is required." (PMID 34738872, 2022). "MM cells secrete VEGF and FGF-2 that induce the cells of the tumor microenvironment to secrete their own VEGF, FGF-2, and HGF, able to recruit and activate the MM-associated macrophages." (PMID 35158878, 2022). "As expected, knockdown of FGF-2 in NPC significantly increased the anti-tumor activity of the VEGF blockade, with the tumor inhibition rate improved to nearly 50%." (PMID 35985991, 2022).